CMTR1 (cap methyltransferase 1)
Diseases named in the same sentence as CMTR1 in open-access papers:
CMTR1 is named in the same sentence as 15 diseases in open-access papers, as found by Europe PMC text mining. Sharing a sentence is not in itself a finding about the gene and the disease. The quoted sentences say what the papers report.
viral infection (9 papers, 2015 to 2024). "The cap-snatching virus, influenza A virus (IAV), requires host cell CMTR1 phosphorylation for viral infection." (PMID 38923463, 2024). "CMTR1, also called IFN-stimulated gene 95 kDa protein (ISG95), is elevated by a viral infection and required to promote IFN-mediated induction of ISGs and the antiviral response." (PMID 37024465, 2023). "CMTR1, also called IFN-stimulated gene 95 kDa protein (ISG95), is elevated by viral infection in a variety of cells." (PMID 37024465, 2023). "Previous studies have shown that CMTR1 is an ISG that is upregulated in response to multiple stimuli, including type I and type II IFN, as well as viral infection and multiple pathogen-associated molecular patterns (PAMPs) which induce IFN (32, –, 34)." (PMID 32404510, 2020). "To test if CMTR1 has potential interactions with Xofluza, we pre-treated WDR7, CCDC115, TMEM199, and CMTR1 polyclonal KO cells with increasing doses of Baloxavir (active form of the drug) prior to PR8 virus infection and measured changes in infectivity." (PMID 31919360, 2020). "While all four KO cell lines and wild type cells displayed a dose-dependent reduction in viral infection rate, CMTR1 KO cells demonstrated the most drastic decrease in infectivity with increasing dose of Baloxavir treatment." (PMID 31919360, 2020). "CMTR1 was first characterised as KIA0082/ISG95, a protein implicated in the response to interferon treatment and viral infection." (PMID 30312682, 2019). "Therefore, although CMTR1 phosphorylation is required for the interferon response, which can suppress aspects of viral infection, in the context of IAV infection, CMTR1 phosphorylation acts as a pro-viral factor." (PMID 38923463, 2024). "Thus, by regulating mRNA stability, and transcriptional expression of interferon‐induced genes, CMTR1 may play an important role in regulating genes involved in immune responses to viral infections." (PMID 26734457, 2015). "CMTR1 is a mRNA methyltransferase and a known regulator of protein expression of IFN‐stimulated genes to restrict viral infection." (PMID 33973408, 2021). "Since viral infections are the main causes of asthma exacerbations in children and expression of CMTR1 has been shown to be upregulated in children during asthma exacerbations, this gene and its product might be promising new therapeutic targets that treat viral infections." (PMID 30647901, 2019). "The exact role of CMTR1 in asthma is not clear but could be related to the fact that the transcription of human CMTR1 is interferon-stimulated and CMTR1 participates in cellular defense mechanisms against viral infection." (PMID 30764532, 2019).
asthma (7 papers, 2015 to 2024). "The main finding of this genetic association study is that CMTR1 is associated with an increased risk of asthma exacerbations." (PMID 26734457, 2015). "The strongest association of rs295137 located near the SPATS2L gene (β = 0.4707, SE = 0.1323, p = 0.0004) and the rs2395672 in the intron of the CMTR1 gene with a childhood onset asthma (β = 0.4433, SE = 0.129, p = 0.0006) were established." (PMID 39795959, 2024). "Consistent with the current knowledge of the biological functions of CMTR1, these data point toward a mechanistic role for this gene in the pathogenesis of asthma exacerbations." (PMID 26734457, 2015). "Our studies implicate several new loci, including CMTR1, a novel candidate gene with a potential role in the pathogenesis of asthma exacerbations." (PMID 26734457, 2015). "The mRNA transcript of the gene showed a significant differential expression in nasal lavage samples from patients with asthma during acute exacerbations, which may indicate a role of CMTR1 in the development of this condition." (PMID 39769372, 2024). "CMTR1 also has a potential role in the pathogenesis of asthma exacerbations." (PMID 35327988, 2022). "Furthermore, our studies implicate CMTR1 as a novel candidate gene with potential roles in the pathogenesis of asthma exacerbations." (PMID 26734457, 2015). "Single nucleotide polymorphisms in cap methyltransferase 1 (CMTR1), tripartite motif containing 24 (TRIM24), and membrane associated guanylate kinase, WW and PDZ domain containing 2 (MAGI2) genes were found to be associated with variability in asthma exacerbations." (PMID 38630536, 2024). "However, in vitro and/or in silico analyses provide additional evidence that genes discovered in these GWAS (e.g. GLCCI1, FBXL7, T gene, ALLC, CMTR1) might play a direct or indirect role in asthma/treatment response pathways." (PMID 30647901, 2019).
influenza (3 papers, 2020 to 2024). An acute viral infection of the respiratory tract, occurring in isolated cases, in epidemics, or in pandemics; it is caused by serologically different strains of viruses (influenzaviruses) designated A, B, and C, has a 3-day incubation period, and usually lasts for 3 to 10 days. "However, in the context of influenza infection, inhibition of CMTR1 phosphorylation reduced the expression of the viral protein NS1 and the number of infected cells." (PMID 38923463, 2024). "We also find that CMTR1, a human mRNA cap methyltransferase, is required for efficient viral cap snatching and regulation of a cell autonomous immune response, and provides synergistic protection with the influenza endonuclease inhibitor Xofluza." (PMID 31919360, 2020). "Taken together, these observations warrant further studies into CMTR1 and SHFL as potential influenza virus host factors and targets to modulate influenza pathogenicity." (PMID 36713229, 2022).
gastric cancer (2 papers, 2025). A primary or metastatic malignant neoplasm involving the stomach. "In clinical gastric cancer cases, high levels of SNORA37, CMTR1, ELAVL1, or CD44 were associated with shorter survival and poor outcomes of patients." (PMID 39815331, 2025). "Moreover, the decrease or increase in CD44v6 splicing, CD44v6/CD44s ratio, and CD44v6 expression in SNORA37 silencing or over-expressing gastric cancer cells were restored by transfecting expression vector or shRNA specific for CMTR1 or ELAVL1." (PMID 39815331, 2025). "In addition, there was facilitated or reduced ELAVL1 enrichment on CD44 pre-mRNA in gastric cancer cells with stable over-expression or knockdown of CMTR1, while silencing or ectopic expression of SNORA37 abolished these effects." (PMID 39815331, 2025). "Western blotting assay showed that CMTR1 and ELAVL1 were up-regulated in human gastric cancer tissues than those in paired normal epithelia." (PMID 39815331, 2025). "For instance, SNORA37 interacts with the cap methyltransferase 1 (CMTR1), enhancing its interaction with ELAVL1 and consequently promoting the nuclear retention in modulating alternative splicing of CD44, which drives gastric cancer progression." (PMID 40584410, 2025). "SNORA37 directly binds to cap methyltransferase 1 (CMTR1) to facilitate its interaction with ELAVL1, resulting in nuclear retention and activity of ELAVL1 in regulating alternative splicing of CD44, which indicates the roles of SNORA37/CMTR1/ELAVL1 feedback loop in gastric cancer progression." (PMID 39815331, 2025).
hepatoma (2 papers, 2020 to 2024). "We confirmed that the CMTR1 transcript is induced in response to beta IFN (IFN-β) in human Huh7 liver hepatoma cells and human monocyte THP-1 cells, as measured by reverse transcription-quantitative PCR (RT-qPCR)." (PMID 32404510, 2020). "In liver hepatoma cells and human monocyte cell lines, CMTR1 has little impact on ISG RNA levels but does impact on protein levels, whereas we report that in MEFs, CMTR1 impacts the RNA levels of ISGs." (PMID 38923463, 2024).
Autoimmunity (1 paper, 2020). The occurrence of an immune reaction against the organism's own cells or tissues. "The lack of immune activation in CMTR1 KO cells at resting state makes it a good drug candidate due to its therapeutic window and low risk of autoimmunity." (PMID 31919360, 2020).
colon cancer (1 paper, 2022). "Our findings indicated that DEDD2, GTF2H5, SNRPA1, BICD1, CELF1, and CLK3 were prognostic risk factors for colon cancer, while ADAD1, CMTR1, HNRNPUL1, FTSJ3, WDR43, THUMPD3, SNRPF were prognostic protective factors." (PMID 36212157, 2022).
colorectal cancer (1 paper, 2023). A primary or metastatic malignant neoplasm that affects the colon or rectum. "Our results revealed that CMTR1 expression is higher in colorectal cancer tissues than in normal tissues, and that high CMTR1 expression is associated with poor prognosis in patients with CRC." (PMID 37024465, 2023). "Transcriptomic analysis revealed differential enrichment in the JAK/STAT signaling pathway in colorectal cancer cells with CMTR1 KD." (PMID 37024465, 2023). "Taken together, our data revealed a functional role of CMTR1 in promoting colorectal cancer cell growth both in vitro and in vivo." (PMID 37024465, 2023). "We first generated a murine MC38 colorectal cancer cell line with stable CMTR1 knockdown (sh-CMTR1), and sh-Ctrl/sh-CMTR1 cells were then transplanted subcutaneously into mice." (PMID 37024465, 2023). "The colony formation assay further demonstrated that the number of colonies formed by colorectal cancer cells was obviously reduced by knockdown and increased by overexpression of CMTR1." (PMID 37024465, 2023). "KEGG pathway analysis revealed differential enrichment in the JAK/STAT signaling pathway in colorectal cancer cells with CMTR1 KD." (PMID 37024465, 2023). "To characterize the roles of CMTR1 in cell proliferation, we knocked down and overexpressed CMTR1 in several colorectal cancer cell lines." (PMID 37024465, 2023). "In this study, we found that CMTR1 expression was higher in colorectal cancer tissues than in normal tissues and that CMTR1 expression was associated with poor prognosis." (PMID 37024465, 2023). "Here, we first identified CMTR1 as a novel oncogene in colorectal cancer." (PMID 37024465, 2023). "Since CMTR1 knockdown reduced STAT3 expression and activation, we further examined whether CMTR1 knockdown can enhance the efficacy of PD1 blockade immunotherapy in colorectal cancer by activating tumor cell-intrinsic type 1 IFN signaling." (PMID 37024465, 2023). "Our work revealed that CMTR1 might be an important regulator of the immunosuppressive microenvironment of colorectal cancer." (PMID 37024465, 2023). "However, the functions of CMTR1 in colorectal cancer (CRC), especially its roles in tumorigenesis and immune regulation, remain unclear." (PMID 37024465, 2023). "Although CMTR1 was found to play an important role in colorectal cancer cell proliferation and immune regulation, CMTR1, itself, is not currently targetable and its function in normal cells is poorly understood." (PMID 37024465, 2023).
melanoma (1 paper, 2019). A malignant, usually aggressive tumor composed of atypical, neoplastic melanocytes. "In fact, CMTR1 is alerted in 33% of the melanoma cases majority being mRNA upregulation clearly pinpointing that its alteration might play crucial role in this cancer type." (PMID 31217906, 2019).
retinal degeneration (1 paper, 2024). Degeneration of the retina. "A further large group of su(rdgB) belong to those regulating transcription (XNP, Fne, Yeti, TFIIFβ, TFIIEα, CG33017, Set, CG7839), and Sf3b1, Cmtr1, Rpl10Ab, TFIIFβ, and Sas10 were among those candidates that in addition suppressed retinal degeneration in norpAp24." (PMID 38499328, 2024).
cancer (7 papers, 2019 to 2025). A tumor composed of atypical neoplastic, often pleomorphic cells that invade other tissues. "The role of CMTR1 in these cancers is still to be determined, but its overexpression may cause increased stability or translation of specific oncogene transcripts, leading to tumor development." (PMID 33376192, 2021). "Thus, CMTR1 activity seems to be affected in a cancer-associated mutant context and may be one of the downstream explanations for the JAK3 mutant cancer phenotype." (PMID 30764532, 2019). "Recent studies revealed that CMTR1 is overregulated in various cancers and promotes ribosomal protein gene expression, thereby enhancing tumor growth." (PMID 40725410, 2025). "We discovered that blocking the interaction of CMTR1 with ELAVL1 via SNORA37 knockdown was able to repress tumorigenesis and aggressiveness, indicating the value of SNORA37/CMTR1/ELAVL1 axis as a therapeutic target for cancers." (PMID 39815331, 2025). "Knockdown of CMTR1 inhibited cancer cell growth both in vitro and in vivo, with a concomitant reduction in the expression of cell cycle-related genes, such as CDKN1A, CDK6, and CCND1." (PMID 37024465, 2023). "Intriguingly, we found that CMTR1 controls cancer cell growth and antitumor immunity by binding to the TSS of STAT3." (PMID 37024465, 2023). "In cancer, CMTR1 is overexpressed in T-cell acute lymphoblastic leukemia with JAK3 mutations and undergoes gene rearrangements with ALK, producing a fusion protein promoting non-small-cell lung cancer development." (PMID 33376192, 2021). "However, some mediators of this mark, as for instance CMTR1, are involved in diverse pathologies, among which are asthma and cancer." (PMID 33376192, 2021). "CMTR1 has not been directly linked to cancer, but multiple studies suggest a possible role in tumors." (PMID 30764532, 2019). "Several of these genes, such as CMTR1 and GMPR, have known roles in RNA modification and purine metabolism, respectively, processes that are commonly dysregulated in cancer, particularly in aggressive subtypes like GBM." (PMID 40725410, 2025). "Therefore, we speculate that competitive binding of CMTR1 and TRN2 might regulate nuclear retention of ELAVL1 in cancer cells, which warrants further investigation." (PMID 39815331, 2025). "In addition, Cap methyltransferase 1 (CMTR1) and CMTR2 were both identified as mRNA 2′‐O‐methyltransferases, and Hua enhancer 1 (Hen1), a small RNA 2′‐O‐methyltransferase, was found to be dysregulated in different cancer cells." (PMID 38880983, 2024).
tumor (4 papers, 2019 to 2025). "The results indicated that the mRNA expression of CMTR1 was significantly higher in tumor tissues than in adjacent normal tissues, and paired analysis further revealed that the mRNA expression of CMTR1 in tumor tissues was elevated." (PMID 37024465, 2023). "Immunohistochemical (IHC) staining demonstrated that CRC tumor tissues exhibited significantly higher CMTR1 protein expression than adjacent normal tissues, and that CMTR1 was localized mainly in the nucleus." (PMID 37024465, 2023). "The results showed that anti-PD1 treatment moderately reduced the growth of tumors derived from sh-Ctrl cells, while CMTR1 knockdown further significantly enhanced the inhibition of tumor growth mediated by anti-PD1 treatment." (PMID 37024465, 2023). "We revealed that CMTR1 synergistically controlled tumor cell proliferation and antitumor immunity by binding to the TSS of STAT3." (PMID 37024465, 2023). "In this study, we found that CMTR1 knockdown significantly enhanced the tumor cell response to PD1 blockade by increasing the recruitment of CD8 + T cells." (PMID 37024465, 2023). "Consistent with the TCGA analysis results, CRC tumor tissues had higher CMTR1 protein expression than adjacent normal tissues." (PMID 37024465, 2023). "Overall, it appears that CMTR1 plays a key role in regulating tumor cell proliferation and antitumor immunity." (PMID 37024465, 2023). "CMTR1 protein expression was generally lower in adjacent normal tissues and higher in tumor tissues, and increased with the pathologic stage." (PMID 37024465, 2023). "For example, elevated expressions of CMTR1, TSPYL1, or RPL23AP42 are associated with poorer survival, aligning with their hypothesized roles in promoting tumor progression or interfering with gene regulation." (PMID 40725410, 2025). "To address whether CMTR1 regulates tumor cell proliferation and immune response through STAT3, we overexpressed CMTR1 in STAT3-knockdown RKO cells." (PMID 37024465, 2023). "The results showed that knockdown of STAT3 expression by siRNA decreased RKO cell proliferation, but increased the expression of chemokines and proinflammatory factors and completely reversed the CMTR1-mediated induction of tumor cell proliferation and immune responses." (PMID 37024465, 2023). "In addition, the correlation between CMTR1 protein expression and tumor pathologic stage was verified." (PMID 37024465, 2023). "Furthermore, the efficacy of PD1 blockade immunotherapy was prominently enhanced in the presence of CMTR1 KD via increased infiltration of CD8 + T cells into the tumor microenvironment." (PMID 37024465, 2023). "Several of these genes, such as CMTR1, play critical roles in mRNA cap methylation and immune response regulation, while GMPR and MT-TL1 are involved in metabolic pathways essential for tumor growth." (PMID 40725410, 2025). "We first compared the mRNA expression of CMTR1 in tumor and adjacent normal tissues from the TCGA-COAD cohort to explore the specific role of CMTR1." (PMID 37024465, 2023). "To evaluate the effect of CMTR1 on tumor growth in vivo, we subcutaneously implanted RKO cells infected with lentivirus expressing control shRNA or shRNA targeting CMTR1 into the left inguinal region of nude mice." (PMID 37024465, 2023). "Stable over-expression of CMTR1 or ELAVL1 into HGC-27 cells resulted in increase of growth, tumor weight, CD31-positive microvessels, and Ki-67 proliferative index of subcutaneous xenografts formed in nude mice, accompanied by up-regulation of CD44v, which were prevented by knockdown of SNORA37." (PMID 39815331, 2025). "Immunostaining revealed that the combination of CMTR1 knockdown and anti-PD1 treatment resulted in significantly increased recruitment of CD8 + T cells into the tumor microenvironment compared with that resulting from anti-PD1 treatment or CMTR1 knockdown alone." (PMID 37024465, 2023).
tumor (continued). "Moreover, inhibition of CMTR1 using siRNA reduced RNAPII binding to the STAT3 TSS and subsequently suppressed STAT3 expression and activation, providing important insights into the immune evasion of tumor cells in CRC." (PMID 37024465, 2023). "Since knockdown of CMTR1 has proven effective in stimulating RIG-1, presumably by increasing endogenous mRNAs lacking first transcribed nucleotide O-2 methylation, CMTR1 inhibitors may also have anti-tumour activities." (PMID 30312682, 2019).
infection (3 papers, 2020 to 2024). The state of being infected such as from the introduction of a foreign agent such as serum, vaccine, antigenic substance or organism. "The cap-snatching virus, influenza A, utilizes host CMTR1 phosphorylation to produce the caps required for virus production and infection." (PMID 38923463, 2024). "The impact of CMTR1 phosphorylation on the interferon response is likely to protect cells from a range of infections." (PMID 38923463, 2024). "In addition, members of the interferon-stimulated IFIT family are pro-viral factors that promote the translation of IAV mRNA41,42; therefore, the CMTR1 phosphorylation-dependent expression of IFIT mRNAs may also contribute to efficient infection." (PMID 38923463, 2024). "Similar to previous observation with PR8 and Udorn virus, we showed that A549 cells lacking WDR7, CCDC115, TMEM199 or CMTR1 again displayed lower levels of IAV HA RNA at 16 h post-infection compared to control cells by qRT-PCR." (PMID 31919360, 2020). "Principal component analysis (PCA) revealed significant differences in RNA expression profile between CMTR1 KO cells and wild type cells in the presence of PR8 infection but not at the resting state." (PMID 31919360, 2020).
CMTR1 also shares sentences with these, for which no sentence is quoted: hyperlipidemia (1 paper); Obesity (1).